VIM (vimentin)
Diseases named in the same sentence as VIM in open-access papers (continued):
Sharing a sentence is not in itself a finding about the gene and the disease.
renal cell carcinoma (51 papers, 2007 to 2026). "VIM gene expression and loss of E-cadherin are prognostic markers for cancer-specific survival in renal cell carcinomas." (PMID 25605241, 2015). "Renal cell carcinoma clear cell type comes from renal tubular cells, and its immunophenotype is closer to proximal convoluted tubule epithelium (expressing Vimentin and CD10)." (PMID 36105937, 2022). "Renal cell carcinoma is also a well-known clear cell tumor, and its immunohistochemical features include negativity for vimentin, CD10, and S-100 protein." (PMID 33026548, 2020). "TNF-α induced EMT in renal cell carcinoma by suppressing E-cadherin expression and promoting Vimentin and MMP-9 protein expression." (PMID 31068208, 2019). "Currently, it is still common practice in routine pathology to differentiate renal cell carcinomas from carcinomas of histogenetically different origins by using immune histology with cytokeratins and Vimentin." (PMID 25944973, 2015). "Vimentin expression is regulated by many factors, such as microRNA-138, which inhibits migration and invasion by directly targeting vimentin in renal cell carcinoma." (PMID 25431208, 2014). "In terms of the shared molecular mechanisms underlying periodontitis and renal cell carcinoma, six genes (IKZF1, LGALS1, LSP1, MNDA, VIM and WAS) were consistently upregulated in both disease tissues, indicating their potential involvement in the common pathogenesis of the two diseases." (PMID 42157182, 2026). "In the gland-like structures formed by human renal cell carcinoma cells, the intracellular localization of Vimentin is most concentrated at the basal pole, indicating cell polarity has a close relationship with the subcellular localization of Vimentin." (PMID 37149651, 2023). "In addition, we also found that RBM10 can upregulate the expression of E-cadherin, downregulate the expression of Vimentin, and inhibit the migration of renal cell carcinomas (RCC)." (PMID 37509501, 2023). "Additional immunohistochemical markers used to diagnose RCC include pan-keratin AE1/AE3, renal cell carcinoma (RCC) antigens, and vimentin." (PMID 40218288, 2025). "TNF-α has also been shown to induce EMT and promote renal cell carcinoma (RCC) tumorigenesis and invasiveness by suppressing E-cadherin, upregulating vimentin, and increasing MMP9 expression." (PMID 39003350, 2024). "This vimentin-pancytokeratin co-expression could be suggestive of a sarcomatoid carcinoma; however, the dysplastic changes found nearby indicate a renal cell origin of the tumour (renal cell carcinoma with sarcomatoid differentiation)." (PMID 29182526, 2017). "Immunohistochemical analysis showed strong positive staining for CD10, vimentin, and EMA, supporting the diagnosis of renal cell carcinoma RCC." (PMID 40909959, 2025). "The pathological tissue from the fracture site tested positive for CAM5.2 and vimentin (membrane) and exhibited weak positivity for CD10, leading to a diagnosis of metastasis from renal cell carcinoma." (PMID 39372036, 2024). "On the contrary, clear cell RCC stains positive for a variety of markers such as vimentin, galectin-3, CD10, CAIX, renal cell carcinoma (RCC), PAX-8, and epithelial membrane antigen (EMA)." (PMID 37990226, 2023). "The tumor cells were diffusely positive for HMB45, Melan-A, CK20, vimentin antibodies, and TFE3, suggesting that the tumor originated from perivascular epithelioid cells, excluding renal cell carcinoma." (PMID 37675231, 2023). "In contrast, the mesenchymal cell markers N-cadherin, Vimentin, and Snail were down-regulated when overexpressing SLC27A2, suggesting that the EMT process is inhibited during renal cell carcinoma progression." (PMID 35927229, 2022). "METTL13 is lowly expressed in renal cell carcinoma, and knockdown of METTL13 promotes the PI3K/AKT/mTOR/HIF-1α pathway leading to migratory ability and invasiveness of renal cell carcinoma cells as well as elevated Vimentin and N-cadherin." (PMID 39289775, 2024).
renal cell carcinoma (continued). "Depletion of CAPN2 could inhibit the expression of N-cadherin, vimentin and MMP9, and overexpression of CAPN2 could enhance N-cadherin, vimentin and MMP9 protein levels in renal cell carcinoma." (PMID 35707527, 2022). "Case 3 tumour (5 mm) is not immuno-positive other than for vimentin; the diagnosis of renal cell carcinoma is being made on the histological aspect on H&E." (PMID 33808971, 2021). "In renal cell carcinoma, NR2C2 could promote renal cell carcinoma metastasis via HGF/Met and miR490-3p/vimentin signals." (PMID 34956884, 2021). "CD10, Vimentin and RCC were all positive and all are specific for renal cell carcinoma." (PMID 29147330, 2013). "However, vimentin immunostain did not prove to be useful in differential diagnosis of subtypes of renal cell carcinoma." (PMID 19558708, 2009). "Vimentin and vinculin did not contribute much in differentiating subtypes of renal cell carcinomas." (PMID 19558708, 2009). "Renal cell carcinoma is typically negative for CK7 and CK20, but positive for RCC antigen, CAM 5.2, Vimentin, and PAX 8, in contrast to our case presented here." (PMID 25124389, 2014). "Moderately differentiated metastatic clear cell renal cell carcinoma was immunohistochemically confirmed - tumor immunophenotype showed positivity for RCC and CD10, and negative for cytokeratin 7 (CK7), cytokeratin 20 (CK20), vimentin and TG." (PMID 41584596, 2025). "Immunohistochemistry indicated FLI-1(+), CD99(+), Vimentin(+), CyclinD1(+), WT-1(+), EMA(+), Bcl2(-), Ki-67(+) 60%, CD56(-), CK(-), CD34(-), Desmin(-), and SMA(-), which suggested that renal clear cell sarcoma may not rule out renal cell carcinoma." (PMID 33859949, 2021). "Pathological examination revealed morphological and immunohistochemical findings in line with metastatic renal cell carcinoma, including positive staining for AE1/AE3 vimentin and CD10, partial positive for RCC, PAX-8, and negative staining for inhibin, CgA, and CA9, the index of Ki-67 is 5%." (PMID 34397852, 2021).
triple-negative breast carcinoma (46 papers, 2009 to 2025). An invasive breast carcinoma which is negative for expression of estrogen receptor (ER), progesterone receptor (PR), and human epidermal growth factor receptor 2 (HER2). "Our previous work also reported TF expression associated to vimentin expression in Triple Negative Breast Carcinoma (TNBC) but also in CTCs isolated from metastatic breast cancer patients." (PMID 35805061, 2022). "Expression of EMT-associated markers including vimentin has been linked to poor prognosis in triple negative breast cancer." (PMID 34831127, 2021). "Consistently, SUM159, which is a claudin-low triple-negative breast cancer cell line, displayed high levels of vimentin and N-cadherin, along with a loss of E-cadherin expression, compared to MCF7, a widely studied epithelial cell line derived from breast adenocarcinoma." (PMID 32636467, 2020). "To summarise, we found that both Vimentin and Keratin 8/18 accumulated near the nucleus in the triple-negative breast cancer cells." (PMID 38891038, 2024). "The correlation between ZEB1 and vimentin expression in triple-negative breast cancer and metaplastic breast carcinoma tumor cohorts further highlighted its role." (PMID 39256881, 2024). "MAP3K2 has also specifically been demonstrated to regulate the abundance of vimentin in some cancers, such as in triple-negative breast cancer." (PMID 37976356, 2023). "Vimentin is a cytoskeletal protein that is involved in the migration of epithelial cells, and vimentin expression has been linked to EMT, and vimentin expression is increased in triple negative breast cancers." (PMID 34831127, 2021). "Elevated TGFB1-2 levels are correlated with increased aggression in triple-negative breast cancers; their inhibition also decreases the expression of VIM and FN1, genes found up-regulated in our model." (PMID 33922695, 2021). "It has been shown that its presence is correlated with less vimentin expression in breast tumors in general and in non-triple-negative breast cancers and with lesser proliferation in breast cancers in general." (PMID 34638264, 2021). "We demonstrate that sevoflurane treatment modulates vimentin, a mesenchymal-specific IFs protein, expression in triple negative breast cancer cells." (PMID 34199634, 2021). "RNF208 decreases the stability of soluble Vimentin protein through a polyubiquitin-mediated proteasomal degradation pathway, thereby suppressing metastasis of triple-negative breast cancer (TNBC) cells." (PMID 33194647, 2020). "Given the inherent mesenchymal phenotype of triple negative breast cancer cells, we determined the expression of the mesenchymal marker vimentin and the epithelial marker E-cadherin in relation to PRAME expression." (PMID 30602372, 2019). "Although some studies have shown that vimentin expression is a marker for poor prognosis, others have reported that its high expression can sensitize triple-negative breast cancer in vitro and in vivo to the c-Src inhibitor (dasatinib)." (PMID 31614718, 2019). "The MDA-MB-231 cell line belongs to a subset of triple negative breast cancers that also express Vimentin." (PMID 21767405, 2011). "The widespread expression of vimentin across all cell lines further underscores the mesenchymal traits common in aggressive cancer phenotypes and carries poor prognosis, particularly in cases of triple-negative breast cancer." (PMID 40646890, 2025). "Interestingly, a recent study demonstrated that the partial EMT in vimentin-positive carcinoma is required for metastasis in triple-negative breast cancer preclinical models." (PMID 39419548, 2025). "Studies have shown that vimentin enhances triple-negative breast cancer (TNBC) aggressiveness and resistance to chemotherapeutic agents, and withaferin A, an inhibitor of vimentin, could be a major player in combating drug resistance and the recurrence of TNBC." (PMID 37259311, 2023).
triple-negative breast carcinoma (continued). "The presence of MR correlates positively with triple negative breast cancer type, its cytoplasmic presence with node-negativity, more differentiated tumor cells and lesser proliferation and is related to reduced expression of vimentin and increased expression of SIP1 in TNBCs." (PMID 34638264, 2021). "In non-triple-negative breast cancers, β-catenin alteration also showed a positive correlation with infiltration levels of intratumoral and total TAMs (p = 0.010, p = 0.035, respectively), and vimentin expression was positively correlated with infiltration levels of intratumoral TAM (p = 0.048)." (PMID 25884955, 2015). "In our study, the expression levels of Vimentin, Snail, and Slug, which act primarily on the EMT pathway, were decreased by the miR-22-3p overexpression and galectin-1 suppression by siRNA in triple-negative breast cancer cells." (PMID 39996781, 2025). "Specifically, in triple-negative breast cancer (TNBC), RING finger protein 208 (RNF208), an estrogen-inducible E3 ligase, targeted soluble vimentin for polyubiquitin-mediated proteasomal degradation, thereby suppressing metastasis." (PMID 36631457, 2023). "In agreement with this study, ATG7 was shown to inhibit EMT in triple-negative breast cancer cells (TNBC) by upregulation of E-cadherin and downregulation of N-cadherin, SMA, and Vimentin." (PMID 40396019, 2022). "Inhibition of TGF-β signaling by down-regulation of TGF-β ReceptorII and alterations in the expression of Snail, Twist, Vimentin, E-cadherin, P-Smad2, β-catenin and GSK3-β by curcumin in triple negative breast cancer cells suppressed EMT." (PMID 25786122, 2015). "Twist protein was highly expressed in the triple-negative breast cancer MDA-MB231 and BT549 cell lines as well as the mesenchymal marker vimentin." (PMID 26295469, 2015). "Interestingly, in the MDA-MB-231 cells, a triple-negative breast cancer cell line, the expression of galectin-1- and EMT-related markers Vimentin and Slug were significantly reduced by miR-22-3p overexpression (p < 0.05 and p < 0.05, respectively)." (PMID 39996781, 2025). "In addition, it would be important to identify common fragile nodes of vimentin, NANOG and CD49f signalling in a more integrated manner in order to evaluate their interest as markers and or new therapeutic targets in triple negative breast cancer." (PMID 34203746, 2021). "In summary, may we conclude that adding vimentin to an immunopanel consisted of basal cytokeratins (CK5/6, 14, 17) appears to be inefficient at predicting survival of triple negative breast cancer patients." (PMID 19695088, 2009). "Vimentin could be identified as a protein overexpressed in tumor cells of triple-negative breast cancer, unlike their receptor-positive counterparts." (PMID 36769215, 2023). "Moreover, comparison of the expression of UTX, Vimentin, and GATA transcription factor family in normal and triple-negative breast cancer samples using the TCGA database also show marked downregulation of GATA3 and UTX, whereas GATA6 was significantly upregulated." (PMID 31685800, 2019). "In triple negative breast cancers (estrogen, progesterone, and HER-2 negative), vimentin expression is correlated with poor prognosis as well as an aggressive and metastatic phenotype." (PMID 24069380, 2013).
endometrial cancer (44 papers, 2008 to 2025). Primary or metastatic malignant neoplasm involving the endometrium (mucous membrane that lines the endometrial cavity). "We report in a large multicentre study, that 8% of women diagnosed with endometrial cancer exhibit loss of vimentin expression in preoperative samples." (PMID 39516342, 2024). "The aim of this study was to validate that loss of vimentin expression serves as a robust marker of recurrence in endometrial cancer." (PMID 39516342, 2024). "Loss of vimentin expression has emerged as a potential marker for predicting recurrence in low-risk endometrial cancer patients." (PMID 39516342, 2024). "In conclusion, we here present data from a large collection of preoperative samples from endometrial cancer patients showing that loss of vimentin expression predicts lymph node metastases and poor prognosis." (PMID 39516342, 2024). "Surprisingly, low epithelial vimentin expression was reported in endometrial cancer with a high risk of recurrence, as confirmed in 518 samples by immunohistochemistry." (PMID 37833976, 2023). "Most importantly, low epithelial vimentin expression is associated with high-risk of recurrence in low-stage endometrial cancer, an important distinction from other cancer types where vimentin is linked to worse patient outcome." (PMID 37146405, 2023). "In previous study, low MAP2K4 expression and positive Vimentin expression were reported to be associated with poor prognoses in endometrial carcinoma." (PMID 31761784, 2019). "As the field of defining endometrial cancer molecular subgroups evolves for prognostication and treatment stratification, we explored whether loss of vimentin could identify patients with poor prognosis within the defined molecular subgroups." (PMID 39516342, 2024). "Interestingly, we recently identified loss of vimentin as a potential marker for recurrence in endometrial cancer, including for tumors confined to the uterus (FIGO stage 1)." (PMID 39516342, 2024). "Vimentin status in endometrial cancer may add valuable prognostic information to better risk stratify patients." (PMID 39516342, 2024). "Expression of miR-424 is associated with epithelial cellular morphology, increased expression of E-cadherin and decreased expression of vimentin, while decreased expression of miR-424 is associated with increased proliferation and migration in endometrial cancer cells." (PMID 36052252, 2022). "Interestingly, loss of vimentin was also highly significantly associated with poor recurrence-free survival when including all histologic types of endometrial cancers (Log rank p = 0.007) and in the subgroup of patients with endometrioid tumors (Log rank p = 0.005, data not shown)." (PMID 37146405, 2023). "Vimentin expression was evaluated using immunohistochemistry in 1483 patients diagnosed with endometrial cancer across 14 hospitals in Europe." (PMID 39516342, 2024). "Vimentin expression in preoperative samples from 1483 women diagnosed with endometrial cancer was evaluated by immunohistochemistry using a staining index (SI), ranging from strong expression (SI 9) to loss of expression (SI 0)." (PMID 39516342, 2024). "A favorable prognosis of retained vimentin expression in endometrial cancer has also been reported previously by us and others, supporting our findings." (PMID 39516342, 2024). "According to the literature, in the genital area, vimentin is positive in most endometrial carcinomas, carcinosarcomas, and uterine mucinous carcinomas." (PMID 40729263, 2024). "Conversely, our present study identifies lower expression of vimentin as a biomarker for worse prognosis in low-stage endometrial cancer and points to important differences between cancer types." (PMID 37146405, 2023). "Mesenchymal markers such as vimentin/fibronectin/N-cadherin have been reported to be over-expressed in endometrial cancer when treated with different cytokines and chemokines." (PMID 36766756, 2023).